ACTR10 (actin related protein 10)
Description:
Part of the dynactin complex that activates the molecular motor dynein for ultra-processive transport along microtubules.
Synonyms: hARP11; ACTR11; ARP10; ARP11
Tractability: Antibody: its Gene Ontology location is reachable by antibodies, with high confidence; the Human Protein Atlas places it where antibodies can reach. PROTAC: ubiquitination databases record sites on it; its protein half-life has been measured.
Gene: Protein-coding gene on chromosome 14 (58,200,080 to 58,235,636, forward strand). Ensembl gene ENSG00000131966.
Subcellular location: Cytoplasm, cytoskeleton
Subcellular location (Human Protein Atlas): Plasma membrane; Vesicles; Connecting piece; Flagellar centriole; Focal adhesion sites; Mid piece; Perinuclear theca; Principal piece
Pathways (Reactome):
Immune System: MHC class II antigen presentation; Neutrophil degranulation
Vesicle-mediated transport: COPI-independent Golgi-to-ER retrograde traffic; COPI-mediated anterograde transport
Cellular responses to stimuli: HSP90 chaperone cycle for steroid hormone receptors (SHR) in the presence of ligand
Gene Ontology:
Molecular function: protein binding; structural constituent of cytoskeleton
Biological process: retrograde axonal transport of mitochondrion; cytoskeleton organization
Cellular component: azurophil granule lumen; cytosol; dynactin complex; extracellular region; ficolin-1-rich granule lumen; nucleus; axon cytoplasm; cytoskeleton
Genetic constraint (gnomAD): Loss-of-function variants: 16 observed, 21.17 expected, observed/expected ratio (o/e) 0.76, 90% interval 0.51 to 1.15. The upper end of that interval is the gene's LOEUF score, 1.15, which puts it in group 5 of 6, group 1 being the genes least tolerant of losing a copy. Missense variants: 259 observed, 281.45 expected, observed/expected ratio (o/e) 0.92, 90% interval 0.83 to 1.02. Synonymous variants: 95 observed, 96.77 expected, observed/expected ratio (o/e) 0.98, 90% interval 0.83 to 1.16.
Homologues: Orthologues: chimpanzee ACTR10 (99% identical), macaque ACTR10 (99% identical), dog ACTR10 (96% identical), rabbit ACTR10 (96% identical), guinea pig ACTR10 (96% identical), pig ACTR10 (96% identical), mouse Actr10 (95% identical), rat Actr10 (95% identical), tropical clawed frog actr10 (84% identical), zebrafish actr10 (75% identical), Drosophila melanogaster Arp10 (37% identical), Caenorhabditis elegans arp-11 (24% identical). Paralogues in human: ACTA2 (28% identical), ACTG1 (28% identical), ACTC1 (28% identical), ACTG2 (28% identical), ACTA1 (28% identical), ACTB (28% identical), ACTBL2 (27% identical), ACTR2 (24% identical), ACTR3B (24% identical), ACTRT2 (24% identical), ACTRT3 (24% identical), ACTL7A (23% identical), and 14 more.
Diseases named in the same sentence as ACTR10 in open-access papers:
ACTR10 is named in the same sentence as 5 diseases in open-access papers, as found by Europe PMC text mining. Sharing a sentence is not in itself a finding about the gene and the disease. The quoted sentences say what the papers report.
metastatic tumor (1 paper, 2022). "By carrying out quantitative real-time PCR (qRT-PCR), we found that, compared with those in the corresponding primary serous ovarian cancer, the mRNA levels of KCTD10, PCMT1, and ACTR10 were significantly increased in metastatic tumor tissues." (PMID 35033172, 2022).
cancer (1 paper, 2019). A tumor composed of atypical neoplastic, often pleomorphic cells that invade other tissues. "Collectively, the DE proteins among the hub-bottlenecks, ACTR10 was the only protein not reported for any types of cancers while the rest, based on previous reports showed some connections with different kinds of cancers." (PMID 32099604, 2019).
ACTR10 also shares sentences with these, for which no sentence is quoted: atherosclerosis (1 paper); inflammation (1); serous ovarian cancer (1).